CRP (C-reactive protein)
Diseases named in the same sentence as CRP in open-access papers (continued):
Sharing a sentence is not in itself a finding about the gene and the disease.
COVID-19 (continued). "Previous studies have reported laboratory examination abnormalities such as reduced lymphocyte count and elevated C-reactive protein and lactate dehydrogenase levels in patients with COVID-19." (PMID 33234724, 2020). "As a result, CRP and LDH exhibited powerful correlations with other indexes, which suggested that CRP and LDH were significant factors associated with the severity of COVID-19." (PMID 32805722, 2020). "Clinicians should consider older male patients with comorbidities, lymphopenia, and a high CRP rate as factors to predict severe forms of COVID-19 earlier." (PMID 33033687, 2020). "In conclusion, this study identified four predictors, i.e., an estimated glomerular filtration rate < 90 ml/min/1.73, elevated cardiac troponin I, C-reactive protein ≥ 25 mg/L and procalcitonin ≥ 0.05 ng/ml, of mortality among COVID-19 patients." (PMID 33365277, 2020). "The laboratory correlate to COVID-19 pathophysiology is observed by lymphopenia and increased C-reactive protein (CRP), procalcitonin (PCT) and D-dimer, among others." (PMID 33391152, 2020). "In our study, CRP reflected the COVID-19 pathogenesis presenting an immune response to this viral infection." (PMID 33329044, 2020). "In COVID-19, CRP correlated with lung lesions, the severity of pneumonia and overall disease severity in the early stage of the disease." (PMID 32668763, 2020). "The plasma CRP level is positively correlated to the severity of COVID-19 on CT performance, and higher level of CRP showed a longer inpatient duration." (PMID 32414383, 2020). "The proportion of COVID-19 patients with elevated CRP was higher than the control groups (60.00 vs. 38.33%, p = 0.0061)." (PMID 33117727, 2020). "This is in controversy with the high secretion of IL-6 in COVID-19 which is an initiator mechanism for C-reactive protein (CRP) production and cytokine storm." (PMID 32754004, 2020). "Our findings were consistent with recent publications, which indicated that the CRP level on admission was a sensitive and early indicator for COVID-19 severity." (PMID 33312067, 2020). "In the current study, a significantly higher CRP level (p=0.005) was observed in severe COVID-19 patients compared with the mild group, as previously reported by other studies." (PMID 33244379, 2020). "Other abnormalities were detected in COVID-19 patients, such as lymphopenia, increased levels of C reactive protein (CRP), lactate dehydrogenase (LDH), erythrocyte sedimentation rate (ESR), and D-dimer." (PMID 32708112, 2020). "COVID-19 severity is associated with the levels of CEA, IL-6, CRP, PCT, Fer, D-dimer, L%, Neu%, and WBC." (PMID 33537326, 2020). "More severe COVID-19 cases are frequently accompanied by laboratory and immunologic changes like C-reactive protein increases, lymphopenia and interleukin (IL)-6 peaks." (PMID 32443442, 2020). "Indeed, severe forms of COVID-19 are associated with particularly high inflammatory and prothrombotic responses, translating into the elevation of the acute-phase reactant C-reactive protein (CRP), low lymphocyte count, and elevation of the fibrin degradation product D-dimer." (PMID 33126565, 2020). "More recently, tocilizumab treatment was shown to reduce systemic inflammation (as measured by C-reactive protein), increase circulating lymphocyte levels, and reduce oxygen therapy needs in a trial of 20 patients with severe or critical COVID-19." (PMID 32556942, 2020). "As in the Chinese cohort of 85 fatal cases, our severe COVID-19 patients had comparable laboratory findings: decreased lymphocytes, increased CRP, and decreased albumin." (PMID 32903324, 2020). "While lymphocytopenia and elevated C reactive protein are common in COVID-19, mortality was only seen in patients who had both low lymphocyte counts (<1000/uL) and profoundly elevated CRP (>30 mg/L) before treatment with TCZ." (PMID 33089038, 2020).
COVID-19 (continued). "The results indicated that the levels of LYM, ALB, A/G, and CRP were significantly correlated with the severity of the COVID-19." (PMID 32746805, 2020). "In our study, the CRP level in the blood of patients with COVID-19 was significantly increased, while there was a significant difference between patients with severe and mild cases." (PMID 32669467, 2020). "We named the model COVID-19-American Association for Clinical Chemistry (AACC) (age ≥60 years, ALB, comorbidity, and CRP), and the score ranged from 0 to 5 points." (PMID 33330318, 2020). "Tocilizumab effectively improves clinical symptoms (lowering body temperature to normal level within one day, significant lowering of C-reactive protein (CRP) after 5 days) and represses the deterioration of severe COVID-19 patients." (PMID 32668803, 2020). "Severe COVID-19 has been found in patients with high CRP and PCT levels, and high CRP levels have been identified in patients with migraine with relative high frequency (seven or more days with headache per month) and chronic migraine, and migraine with aura." (PMID 33391152, 2020). "In our review, several markers are commonly used to identify the thrombo-inflammatory nature of COVID-19 (e.g., D-dimers, CRP, ferritin, fibrinogen, antiphospholipid antibodies, LDH, and troponin)." (PMID 33123082, 2020). "During the outbreak of COVID-19, wo need to be more alert to the levels of pro-inflammatory neutrophils and CRP after cancer patients infected with COVID-19, so as to better give corresponding treatment measures." (PMID 33192519, 2020). "In summary, our study showed CRP, D-dimer, LDH, PCT are the high risk factors related with COVID-19." (PMID 33166991, 2020). "A systematic review summarized the clinical manifestations of 108 pregnant women with confirmed COVID-19 and most of them presented fever (68%) and coughing (34%), and lymphocytopenia (59%) with elevated C-reactive protein (70%)." (PMID 33330308, 2020). "Our findings suggest that older age, admission D-dimer (>1000 ng/mL), CRP (>200 mg/lL), and lymphopenia (1.0 x103/microliter) provide a reliable panel of tools to evaluate patients hospitalized with COVID-19." (PMID 32726241, 2020). "Significant predictors of mortality from COVID-19 in patients with DM were lymphocyte count, creatinine and C-reactive protein (CRP) level (all P-values < 0.05)." (PMID 32641974, 2020). "Previously, small-scale studies have evaluated changes in IL-6 and CRP concentrations for COVID-19 patients, the correlation between IL-10 and CRP is still unclear." (PMID 32475230, 2020). "Blood parameters usually chosen for COVID-19 severity monitoring (lymphocytes, ferritin, CRP, LDH, and d-Dimer) showed AUC values ranging between 0.468 and 0.682." (PMID 33182268, 2020). "The survival curve analysis showed that higher C-reactive protein (≥5mg/L) plus any other abnormalities of lymphocyte, blood urea nitrogen or lactate dehydrogenase significantly predicted poor prognosis of COVID-19 infected elderly patients." (PMID 32651993, 2020). "The serum levels of IL-6 and CRP can effectively evaluate the severity and predict the prognosis in patients with COVID-19." (PMID 33062712, 2020). "Model 3, which consisted of the troponin I group and CRP, showed that troponin I (p = 0.009) was an independent significant predictor of mortality in patients with COVID-19." (PMID 33322097, 2020). "For some patients in the mild COVID-19 group, the value of CRP was still normal, but the value of SAA increased significantly." (PMID 32713370, 2020). "Meanwhile, the statistical analyses indicated that the development of COVID-19 brought about a significant increase in the content of CRP and SAA (P < 0.01), and a decline in the content of C3, C4 and PA (P < 0.01)." (PMID 32713370, 2020). "CRP level significantly increases in COVID-19 patients due to inflammatory reaction and tissue destruction." (PMID 32894449, 2020).
COVID-19 (continued). "A systematic review showed that the most reported predictors of poor prognosis in patients with COVID-19 are age, sex, C-reactive protein (CRP), lactate dehydrogenase (LDH), lymphocyte count, and features derived from CT scans." (PMID 32998323, 2020). "COVID-19 patients with significantly elevated CRP levels (e.g., > 100 μg/mL) more readily reflect advanced tissue damage and pathologies associated with cytokine storm, coagulation abnormalities, and multiple organ failure." (PMID 32588812, 2020). "Patients with severe or fatal COVID-19 showed significantly higher levels of inflammatory factors, such as CRP, interleukin-6 (IL-6), interleukin-2 (IL-2) and interleukin-7 (IL-7)." (PMID 32719804, 2020). "Receiver operating characteristic analysis concluded LDH (area under the curve [AUC]: 0.875), D-dimer (AUC: 0.803), and PCT (AUC: 0.769) were superior biomarkers to ferritin (AUC: 0.714) and CRP (AUC: 0.711) in predicting the fatality of COVID-19." (PMID 32913691, 2020). "The patients shared relatively similar laboratory findings except 3% of the non-COVID-19 patients who had lympho-neutropenia and 22.6% had high levels of C-reactive protein." (PMID 33088398, 2020). "At our institution, additional diagnostic data from chest imaging and blood tests such as lymphocyte count and CRP are considered in clinical decision making when assessing patinets for COVID-19." (PMID 32905045, 2020). "As expected, there was a statistically significant difference with respect to lower lymphocyte count, elevated ferritin and CRP in the COVID-19 positive group." (PMID 33106441, 2020). "Coagulopathy in the context of severe inflammation (elevated D-dimer, fibrinogen, or C-reactive protein levels) has been reported in patients with COVID-19." (PMID 33291502, 2020). "Clinical markers characteristic of cytokine storm include increased circulating C-reactive protein and erythrocyte sedimentation rate, and observational studies have noted upregulation of a variety of circulating cytokines in COVID-19." (PMID 32556942, 2020). "Anemic patients had increased levels of inflammation markers such as interleukin-6 and C-reactive protein and survived a more severe course of COVID-19." (PMID 33087116, 2020). "High rates of biological markers such as ferritin, CRP, D-dimer, and LDH were associated with severe forms of COVID-19, as well as a rate of lymphocytes < 0.8 x 109/L." (PMID 33033687, 2020). "Complement factors were major components that clogged CRP adsorber columns during the treatment of critically ill patients with COVID-19 prompting further studies on a role of complement in COVID-19 infection." (PMID 33584662, 2020). "The values of cytokines and CRP were significantly higher in patients with COVID-19 than in healthy controls (P < 0.01), suggesting an activation of immune response against SARS-CoV-2 infection." (PMID 32475230, 2020). "Several reports also focused on lymphopenia and high levels of C-reactive protein in COVID-19 patients." (PMID 32257537, 2020). "Increased inflammation-related biomarkers were found in COVID-19 patients, including interleukin-6 (IL-6), C-reactive protein (CRP), ferroprotein, and so on." (PMID 33349241, 2020). "Our findings concluded that D-dimer, PCT, and LDH were superior to serum ferritin and CRP as an effective biomarker in predicting the fatality of COVID-19." (PMID 32913691, 2020). "Consistent with a recrudescence of COVID-19, the patient’s CRP increased, and his lymphocyte count fell." (PMID 33318491, 2020). "More patients in the severe COVID-19 group presented with C-reactive protein (CRP) values in the highest tertile (46 vs. 22% for mild/moderate disease)." (PMID 32903324, 2020). "There was a statistically significant difference in the number of blood lymphocytes, neutrophils, and C-reactive protein (CRP) between pregnant COVID-19 patients and control women." (PMID 33117727, 2020).
COVID-19 (continued). "In the context of COVID-19 with high levels of D-Dimers, CRP and fibrinogen at admission, the low level of fibrin monomers allowed us excluding a disseminated intravascular coagulation process." (PMID 32676824, 2020). "Pro-inflammatory neutrophils and CRP can be used as independent predictors of the severity and the adverse clinical outcomes of COVID-19." (PMID 33192519, 2020). "Based on our finding, lymphocyte count, creatinine and CRP level were significant predictors for death of COVID-19 in diabetic patients." (PMID 32641974, 2020). "Patients with severe COVID-19 were more likely to have dyspnea and lymphocytopenia with hypoproteinemia, and their levels of alanine aminotransferase, lactate dehydrogenase, C-reactive protein, ferritin, and D-dimer increased." (PMID 33232275, 2020). "The severe COVID-19 group was characterized by significantly lower lymphocyte count and higher serum level of C-reactive protein than the mild COVID-19 group on the day of blood sampling." (PMID 32651212, 2020). "CRP is used clinically as a biomarker for various inflammatory conditions; a rise in CRP levels is determined in both COVID-19 and influenza groups." (PMID 33148349, 2020). "Another study demonstrated that the mean level of CRP is higher in severe COVID-19 patients compared to mild cases." (PMID 33244370, 2020). "COVID-19 patient-level data show a notable odds ratio of 3.4 for high CRP in severe COVID-19 patients." (PMID 33233560, 2020). "In a small study of COVID-19 patients, a combination of IL-6 levels > 80 pg/mL and CRP levels > 97 mg/L were highly predictive of the need for mechanical ventilation." (PMID 32922297, 2020). "Other indices including neutrophil count and CRP levels of the pregnant COVID-19 patients were significantly higher than those of the control pregnant women." (PMID 33117727, 2020). "Another early mortality risk score for hospitalised patients was developed from only 75 patients with COVID-19 and based on only age and C-reactive protein level." (PMID 33288840, 2020). "Here, we analyzed the dynamic changes of some inflammatory markers after anticoagulant treatment and found improved CRP expression after anticoagulant therapy, which is a frequent prognostic factor for COVID-19 that reflects the inflammatory process." (PMID 33318314, 2020). "In patients with COVID-19, C-reactive protein (CRP) is usually increased on presentation while PCT is often low." (PMID 33023606, 2020). "It was identified that serum IL-6, CRP, procalcitonin, and lactate at the time of being admitted to hospital predicted poor outcomes of COVID-19." (PMID 33239109, 2020). "In patients with COVID-19 and headache, there was at least one abnormal laboratory value in the first measure, being the most common abnormal increased CRP levels." (PMID 33391152, 2020). "Several biomarkers like IL-6, presepsin (PSP), procalcitonin (PCT), CRP, D-Dimer have showed a good function as predictor factors for the clinical evolution of COVID-19 patients (mild, severe and critical)." (PMID 33147871, 2020). "A case of COVID-19 death study found that the CRP increased significantly after the onset of the patient, and lasted for more than 14 days." (PMID 32357808, 2020). "Our retrospective study showed that STEMI patients with COVID-19 had elevated inflammatory markers with mean of their CRP (89.69 ± 30.42 mg/dl) and increased laboratory parameters of thrombosis with mean D-dimer (660.15 ± 360.11 ng/ml)." (PMID 33025310, 2020). "Therefore, it is of interest to evaluate the correlation between comorbidity burden and inflammatory markers-C-reactive protein (CRP) and D-dimer-in 100 hospitalized COVID-19 patients at a tertiary care center in Madhya Pradesh, India." (PMID 42109327, 2026).
COVID-19 (continued). "To gain a comprehensive understanding of the demographic factors and laboratory biomarkers’ impact on ARDS in COVID-19, we conducted a correlation analysis between age, BMI, CRP, hematological biomarkers (neutrophil, lymphocyte, and NLR), and cytokines (IL-10 and TNF-α), with PaO2/FiO2." (PMID 40761632, 2025). "Severe coronavirus disease 2019 (COVID-19) is characterized by systemic hyperinflammation with cytokine and chemokine release, alongside elevations in conventional laboratory biomarkers such as C-reactive protein (CRP), ferritin, and procalcitonin (PCT)." (PMID 41373577, 2025). "In a sub-group analysis with TyG as the index for insulin resistance based on past COVID-19 status, age, BMI, triglycerides and CRP turned out as the statistically significant (P < 0.05) predictors of insulin resistance in participants with past COVID-19 status." (PMID 40273152, 2025). "However, we did find that in COVID-19 patients, fibrinogen levels primarily correlated with CRP, whereas in non-COVID-19 patients, they demonstrated correlations with CRP, troponin I, IL-6, and platelet count." (PMID 40364223, 2025). "In patients with COVID-19 and confirmed PE, very high CRP and IL-6 levels, together with extensive parenchymal involvement, identify a subgroup with a markedly increased risk of invasive mechanical ventilation and death, even when D-dimer and thrombus location are not strikingly different." (PMID 41463074, 2025). "CRP levels were significantly elevated in the COVID-19 group (8.45 mg/L vs. 1.08 mg/L, p = 0.003)." (PMID 41012624, 2025). "Biomarkers such as C-reactive protein and, in the near future, insights into corticosteroid-related immune repair mechanisms in COVID-19 may aid in identifying corticosteroid-responsive phenotypes." (PMID 40598558, 2025). "NLR predicts COVID-19 prognosis, while CRP is a known acute-phase protein in pneumonia." (PMID 40915180, 2025). "COVID-19 severity is linked to elevated levels of inflammatory mediators, including cytokines (e.g., IL-2, IL-7, IL-10, IFN-γ, and TNF-α) and chemokines (e.g., G-CSF, MCP1, MIP1α, and CXCL10), as well as markers like C-reactive protein, ferritin, and D-dimers." (PMID 40649865, 2025). "Moderate and severe forms of COVID-19 are accompanied by an increase in inflammatory biomarkers, such as CRP, procalcitonin, the neutrophil to lymphocyte ratio, and hemostasis parameters (activated partial thromboplastin time, prothrombin time, D-dimers, and fibrinogens)." (PMID 40215478, 2025). "Previous studies have already shown that individuals with COVID-19 had high levels of some inflammatory mediators in more severe cases of the disease, such as C-reactive protein, D-dimer, bilirubin, urea, and IL-1β, IL-6, IL-8, IL-10, IL-18, IFN, TNF-α cytokines." (PMID 39861879, 2025). "Another significant difference between adults and pediatric COVID-19 patients is the level of CRP." (PMID 39967737, 2025). "Additionally, severe COVID-19 patients exhibited higher inflammatory markers (CRP, neutrophil count) and lower lymphocyte counts." (PMID 41301713, 2025). "In COVID-19, children aged 7–24 months more frequently had higher CRP levels (OR 1.108 [1.001–1.226]) and chronic diseases (OR 7.59 [1.115–51.64]), whereas in those >24 months, only CRP was significant (OR 1.16 [1.047–1.31])." (PMID 41305426, 2025). "Anti-SARS-CoV-2 IgG antibodies were detected in 49 out of 56 tested patients (87.5%), and this seroconversion was statistically more common in patients with a more severe course of COVID-19 (as indicated by abnormal chest X-ray results and higher CRP and D-dimer concentrations)." (PMID 40969806, 2025). "In COVID-19, children aged 7–24 months more frequently had higher CRP levels (OR 1.108, 95CI% 1.001–1.226) and chronic diseases (OR 7.59, 95CI% 1.115–51.64), whereas in those older than 24 months, only CRP was significant (OR 1.16, 95CI% 1.047–1.31)." (PMID 41305426, 2025).